Y_RNA (Y RNA )
Gene: Miscellaneous RNA gene on chromosome 15 (59,408,905 to 59,409,015, forward strand). Ensembl gene ENSG00000200252.
Homologues: Paralogues in human: Y_RNA (86% identical), Y_RNA (85% identical), RNY1 (84% identical), Y_RNA (83% identical), Y_RNA (82% identical), Y_RNA (81% identical), RNY1P7 (80% identical), Y_RNA (80% identical), RNY1P11 (79% identical), Y_RNA (79% identical), Y_RNA (78% identical), RNY1P3 (77% identical), and 94 more.